PIN1 (peptidylprolyl cis/trans isomerase, NIMA-interacting 1)
Diseases named in the same sentence as PIN1 in open-access papers (continued):
Sharing a sentence is not in itself a finding about the gene and the disease.
pancreatic cancer (continued). "Thus, a PIN1-induced antioxidant and cellular detoxification program is expected to provide a therapeutic benefit for pancreatic cancer." (PMID 36834887, 2023). "Based on this, we speculate that the regulatory mechanism of PIN1 mediated by stromal mechanical forces in pancreatic cancer might involve remodeling of the cytoskeletal system." (PMID 36834887, 2023). "Meanwhile, we constructed pancreatic cancer cells with PIN1 overexpression, and the results demonstrated that overexpression of PIN1 in cells cultured on a soft substrate could re-activate the upregulation of NRF2 and inhibit the ROS production." (PMID 36834887, 2023). "Moreover, we found that hard matrix-cultured pancreatic cancer cells induced the upregulation of PIN1 expression." (PMID 36834887, 2023). "Further studies showed that this phenomenon might be related to the upregulation of NRF2 expression induced by PIN1 in hard matrix-cultured pancreatic cancer cells." (PMID 36834887, 2023). "Here, we demonstrated that the physical properties of the stroma could regulate the expression of PIN1 in pancreatic cancer cells." (PMID 36834887, 2023). "In this study, SR values were positively correlated with the abundance of PIN1 in pancreatic cancer tissues, suggesting that hard pancreatic cancer may play a biophysical role in the regulation of intracellular PIN1 expression." (PMID 36834887, 2023). "Studies revealed overexpression of Pin1 in both mRNA and protein levels for oral squamous cell carcinoma, gastric cancer, and acute myeloid leukemia, and only at the protein level in colorectal cancer, osteosarcoma, and pancreatic cancer." (PMID 37508437, 2023). "Furthermore, they also showed that inhibition of Pin1 activity suppressed the downstream c-Myc target genes and reduced tumor progression in both in vitro and in vivo neuroblastoma and pancreatic cancer models." (PMID 37508437, 2023). "Additionally, PIN1-induced IL-18 expression promotes pancreatic cancer cell proliferation and motility, whereas PIN1 knockdown inhibits the tumor-promoting effect of IL-18." (PMID 35954317, 2022). "To determine whether selective Pin1 inhibition in CAFs affects their ability to act on pancreatic cancer cells, we conducted the indirect co-culture of pre-formed pancreatic cancer spheroids with CAFs." (PMID 35879297, 2022). "Pin1 could promote metastasis via activation of the NF-κB-interleukin (IL)-18 feedback loop in pancreatic cancer cells." (PMID 33807199, 2021). "In addition, recombination human IL‐18 (rhIL‐18) enhanced the proliferation and invasiveness of pancreatic cancer cells, whereas this tumour‐promoting effect were eliminated by Pin1 knockdown." (PMID 32347623, 2020). "Thus, we found that Pin1 potentially activated NF‐κB signalling and correlated with IL‐18 expression in pancreatic cancer cells." (PMID 32347623, 2020). "Pin1 has been reported to promote pancreatic cancer metastasis in vitro and in vivo." (PMID 32347623, 2020). "Thus, targeting Pin1 has emerged as a viable clinical strategy, with one recent study finding that Pin1 inhibition in a pancreatic cancer model disrupted multiple cancer pathways and the immunosuppressive microenvironment, rendering it eradicable by immunochemotherapies." (PMID 38727267, 2024). "A recent study pointed out that a PIN1 inhibitor could downregulate the proliferation of pancreatic cancer cells, reduce collagen deposition, and inhibit the activation and proliferation of tumor-associated fibroblasts (CAFs) in the tumor stromal microenvironment." (PMID 36834887, 2023). "Therefore, we hypothesized that the highly fibrotic stroma in the tumor microenvironment might be an important factor altering the effect of PIN1 in pancreatic cancer cells." (PMID 36834887, 2023). "Both Pin1 and IL‐18 could enhance the NFκB activity in pancreatic cancer cells." (PMID 32347623, 2020).
pancreatic cancer (continued). "Empirical data has evidenced that the strategic inhibition of targets such as Pin1, MEK, STAT3, ARG1 can significantly elevate the response rates of pancreatic neoplasms to anti-PD1 therapy, enable more pancreatic cancer patients to benefit from immunotherapy." (PMID 40433359, 2025). "MLK3-dependent Pin1 phosphorylation has been shown to promote Pin1 nuclear translocation and activation of oncogenic GLI1 in pancreatic cancer cells." (PMID 38745861, 2024). "To decipher effects of selective Pin1 inhibition in CAFs on pancreatic cancer, here we formulate a DNA-barcoded micellular system (DMS) encapsulating the Pin1 inhibitor AG17724." (PMID 35879297, 2022). "Here the authors report the design of a DNA-barcoded micellular system functionalized with antibodies targeting CAFs and a T cell recruiting aptamer to deliver the PIN1 inhibitor AG17724, showing antitumor response in preclinical models of pancreatic cancer." (PMID 35879297, 2022). "Secondly, we showed that Pin1 inhibitor AG17724 delivery, via antiCAFs-DMS, into CAFs might be an alternative and potent way for pancreatic cancer treatment." (PMID 35879297, 2022). "We previously demonstrated that elevated Pin1 expression in PDAC was an indicator of a poor prognosis and a sign of a maintained redox balance via the c‐Myc/NRF2/ARE axis, which provides antioxidation protection in Kras‐mutant pancreatic cancer cells." (PMID 32347623, 2020). "We herein checked them, and we observed that, for pancreatic cancer cells, Pin1 and these three relative proteins were at similar levels no matter whether they were treated with phosphate-buffered saline (PBS), AG17724, or antiCAFs-DMS." (PMID 35879297, 2022). "Given that, the pharmacological inhibition of PIN1 and CDK1 could be promisingly used in the therapy of these cancers especially TNBC and pancreatic cancers featured with worse prognosis and no targeted therapies." (PMID 36813923, 2023).
diabetes (16 papers, 2007 to 2024). "Pin1 has now been linked to a number of diseases, including diabetes, NASH, obesity, osteoporosis, and cardiac hypertrophy." (PMID 38892011, 2024). "In this regard, several studies described a prominent role of Pin1 in vascular changes associated to diabetes, where endothelial dysfunction represents an initial process in its vascular manifestations." (PMID 34943794, 2021). "We aimed to explore the effects of the VDR agonist on diabetes-associated endothelial dysfunction and the role of Pin1 in this process." (PMID 29849865, 2018). "Recently, it has also been reported that upregulation of Pin1 protein expression and activity was involved in the pathogenesis of diabetes-associated endothelial dysfunction through facilitating mitochondrial translocation of the prooxidant adaptor p66Shc." (PMID 29849865, 2018). "Pin1 levels were higher in the presence of diabetes and associated with impaired endothelial function and higher oxidative stress biomarkers, consistent with a connection between mitochondrial DNA damage and vascular function in patients." (PMID 27036979, 2016). "This study elucidated the role played by the Pin1/BRD4 pathway in diabetes- induced GC progression, and provides a theoretical basis for finding and screening new targets for antidiabetic tumor drugs." (PMID 35461311, 2022). "Mitochondrial oxidative signaling contributes to alcohol-induced apoptosis, and downregulation of Pin1 can prevent mitochondrial oxidative stress in patients with diabetes." (PMID 26697133, 2016). "We ascertained the effects of Pin1 on obesity and diabetes, since Pin1 expression is increased by a high-fat diet, which is one of the most common causes of obesity." (PMID 28036348, 2016). "Recent studies have shown that Pin1 is related to diabetes, NASH, obesity and other diseases." (PMID 38892011, 2024). "Furthermore, increased PIN1 expression and activity have been found in aortas of diabetic mice and peripheral blood monocytes of type 2 diabetes mellitus patients." (PMID 30534074, 2018). "In that interaction with AMPK, Pin1 may represent a therapeutic target also to treat obesity and diabetes." (PMID 30096758, 2018). "The mutual interaction between GSK-3β and Pin1 become evident also in experimental models of hereditary hemochromatosis, whereas homozygous patients carrying the HFE hemocromatosis mutation have enhanced risk of diabetes (“bronze diabetes”) if untreated." (PMID 30096758, 2018). "Moreover, Pin1 inhibition prevents diabetes-induced expressions of VCAM-1 and MCP-1 and endothelial dysfunction." (PMID 28300760, 2017). "Results of this study suggest that Pin1 down-regulation could be a potential approach in obesity-related dysfunctions, such as high blood pressure, diabetes, non-alcoholic steatohepatitis." (PMID 22412843, 2012). "Therefore, Pin1 may play an important role in the occurrence and development of cognitive dysfunction in diabetes." (PMID 37990376, 2023). "Based on evidence indicating a key role of Pin1 in regulating NO production and vascular homeostasis, alteration of Pin1 levels and/or isomerase activity may be involved in the pathogenesis of vascular pathologies, such as hypertension and diabetes." (PMID 34943794, 2021). "Therefore, we speculate that Pin1 and BRD4 are important regulatory proteins of diabetes that promote macrovascular disease, but the underlying mechanism is still unclear." (PMID 32774672, 2020). "Therefore, it is speculated that PIN1 may be involved in the development of diabetes and diabetic vascular complications." (PMID 30534074, 2018). "Moreover, Pin1 inhibition prevents diabetes-induced endothelial dysfunction." (PMID 28300760, 2017). "Moreover, Pin1 inhibition prevents diabetes-induced endothelial dysfunction via NF-κB signaling." (PMID 28300760, 2017).
diabetes (continued). "Thus, results of this study suggest that Pin1 down-regulation could be a potential approach in obesity-related dysfunctions, such as high blood pressure, diabetes, non-alcoholic steatohepatitis." (PMID 22412843, 2012). "Antagonizing the Pin1/BRD4 pathway may be a feasible method for preventing and treating macrovascular disease in patients with diabetes." (PMID 32774672, 2020). "More generally, the broad range of type 1 immune responses such as infectious diseases (intra and extracellular pathogens) or autoimmunity (diabetes, multiple sclerosis and lupus) that involve or require IFN-γ suggest a role for Pin1 in these processes as well." (PMID 17311089, 2007).
viral infection (15 papers, 2012 to 2025). "Pin1 plays a crucial role in pathogenesis and has been implicated in metabolic disorders, cardiovascular diseases, inflammatory diseases, viral infection, cancer and neurodegenerative diseases such as Alzheimer’s, Parkinson’s and Huntington’s disease." (PMID 36111342, 2022). "These tumors can harbor amplification of the MYCN oncogene, altered pRB phosphorylation by PIN1 gene, or caused by viral infection." (PMID 25602518, 2015). "In addition to cancer and neurodegenerative diseases, Pin1 is associated with viral infections and metabolic disease; however, for brevity, this review will summarily highlight the role of Pin1 in these diseases." (PMID 36111342, 2022). "Viral infection phosphorylates Ser22-Pro23 of the laminin, the main component of the lamina, and Pin1 binds to the phosphorylated site to isomerize the laminin, degrading the lamina structure and allowing viral budding at the nuclear membrane." (PMID 36393854, 2022). "It has been shown that the type 1 interferon system, an innate immunity that mainly acts against viral infection, is negatively regulated by Pin1." (PMID 36393854, 2022). "Pin1 enhances the efficiency of viral infection by promoting uncoating and integration of the human immunodeficiency virus." (PMID 36393854, 2022). "Five potent Pin1 inhibitors, including H-77, were applied for 2 h before virus infection, followed by washing out the Pin1 inhibitors before virus infection." (PMID 34535740, 2021). "Some studies have found that Pin1 is one of these proteins and is closely related to viral infections 20, 110-119." (PMID 33537091, 2021). "For example, during virus infection, Pin1 isomerized viral integrase as well as cellular IRF3 required for efficient virus replication and IRF-3-dependent production of IFN-β, respectively." (PMID 25874604, 2015). "Pin1 also modulates the turnover of the transcription factor IRF3 downstream of toll-like receptor (TLR) 3, and Pin1-null mice were defective in producing IFNβ when challenged with poly (I:C) to mimic viral infection." (PMID 22238658, 2012). "Additionally, Pin1 inhibitors have been reported to suppress the replication of viral DNA, adding another dimension to its regulatory role in viral infection and cellular pathways." (PMID 41477119, 2025). "In the case of viral infections, Pin1 could positively regulate viral replication and propagation in Epstein-Barr virus (EBV), Hepatitis B virus (HBV), and Hepatitis C virus (HCV)." (PMID 36111342, 2022). "In the context of primary viral infection, there is also growing evidence that Pin1 may be co-opted by viral proteins." (PMID 25874604, 2015). "Indeed, TRIM21 was shown to interact directly with IRF3 upon viral infection and to interfere with its interaction with Pin1." (PMID 24586174, 2014). "Thus, the role of Pin1 may play an important regulatory role in determining virus infection and replication efficiency." (PMID 41171811, 2025). "Besides, PIN1 also plays a role in inflammatory diseases and viral infections." (PMID 38627659, 2024). "Research on the application of Pin1 inhibitors and agonists in other related diseases is limited, and more detailed investigations need to be carried out for therapeutic potential, especially in diseases such as viral infection and AD in which the role of Pin1 is relatively clear." (PMID 33537091, 2021). "More specifically, the overexpression of PML-VI augmented the production of IFNβ in U373-MG or HeLa cells stimulated by double RNA or virus infection, and this augmentation was attributed to the ability of PML-VI to recruit Pin1 to PML NBs, and thereby prevent the degradation of phosphorylated IRF3." (PMID 25812002, 2015).
viral infection (continued). "Since Pin1 might also affect different phases of herpesviral replication besides nuclear egress, the inhibitor treatment was not started immediately after virus infection as performed for the GFP-based replication assay." (PMID 27556400, 2016). "Therefore, the interaction of endogenous Pin1 with SUMOylated PMLIV and its recruitment in PML NBs could alter Pin1-induced downregulation of activated IRF3 thus resulting in a higher amount of phosphorylated IRF3 during viral infection." (PMID 24586174, 2014).
gastric cancer (14 papers, 2019 to 2024). A primary or metastatic malignant neoplasm involving the stomach. "According to these results, we confirmed that deficient miR-628-5p expression promotes gastric cancer by upregulating PIN1." (PMID 32703934, 2020). "The deficiency of miR-628-5p attenuates its inhibition on PIN1 expression and following gastric cancer progresses." (PMID 32703934, 2020). "Association between PIN1P1 or PIN1 expression and clinicopathological parameters in gastric cancer." (PMID 37929660, 2024). "To determine whether high expression of PIN1 is related to deficiency of miR-628-5p in gastric cancer, we detected the expression of miR-628-5p in the 24 pairs of gastric cancer and adjacent tissues by qRT-PCR." (PMID 32703934, 2020). "EdU and CCK8 proliferation assays indicated that PIN1 enhanced cell proliferation of gastric cancer and significantly increased gastric cancer cell migration and invasion." (PMID 37929660, 2024). "PIN1 has been proven to promote gastric cancer proliferation and metastasis by activating PI3K/AKT and Wnt/β‐catenin signalling." (PMID 37929660, 2024). "Our findings offer insights into the mechanisms underlying pseudogene lncRNA‐associated gastric carcinoma progression and lay the foundation for further PIN1P1/PIN1‐targeting therapeutical approaches for gastric cancer." (PMID 37929660, 2024). "PIN1P1 expression in gastric cancer tissues showed a positive relationship with PIN1 expression (Spearman r = 0.5079, p < 0.0001)." (PMID 37929660, 2024). "High expression of PIN1 was correlated with poorer overall survival and post‐progression survival in patients with gastric cancer." (PMID 37929660, 2024). "As expected, we confirmed that PIN1 is upregulated in gastric cancer and promotes cancer progression." (PMID 37929660, 2024). "Hyperglycemia also enhances gastric carcinoma proliferation and migration via thr Pin1/BRD4 transcriptional pathway, involved in the hyperglycemia‐induced inflammatory process." (PMID 38751364, 2024). "Recently, researches indicated that PIN1 is also upregulated in gastric cancer, and facilitates its proliferation and chemoresistance." (PMID 32703934, 2020). "To investigate the PIN1-targeted miR in gastric cancer, we predicted miRs that potentially target PIN1 by mirTarbase, targetscan, miRNApath, starbase, and miRanda." (PMID 32703934, 2020). "We firstly demonstrated that miR-628-5p also inhibits the progression of gastric cancer through targeting PIN1 at the 290 region of its mRNA 3′UTR." (PMID 32703934, 2020). "In our research, we detected the mRNA and protein level of PIN1 in eight gastric cancer cell lines and human gastric epithelium cell line (GES)." (PMID 32703934, 2020). "Result showed that, overexpression of PIN1 reverses the miR-628-5p-mediated suppression of gastric cancer." (PMID 32703934, 2020). "In summary, our study demonstrated that deficient miR-628-5p expression facilitates the expression of PIN1, and consequently promotes the progression of gastric cancer." (PMID 32703934, 2020). "The result also indicated that PIN1 is high expressed in majority of gastric cancer tissues (44/66) and positive related with lymph node metastasis and TNM stage." (PMID 32703934, 2020). "MiR-122-5p, miR-331-3p, miR-346, miR-628-5p, and miR-760 reduced the mRNA expression of PIN1 by at least 25% in three or more gastric cancer cell lines." (PMID 32703934, 2020). "Our study provided a potential target for the RNAi-based therapeutic by inhibiting PIN1 in gastric cancer." (PMID 32703934, 2020). "In this research, we revealed that PIN1 not only promotes the proliferation and colony formation of gastric cancer, but also increases its migration and invasion." (PMID 32703934, 2020). "Exogenous expression of miR-628-5p inhibits the progression of gastric cancer that revered by restoring PIN1 expression." (PMID 32703934, 2020). "Recent researches demonstrated that PIN1 promotes the proliferation, colony formation, and chemoresistance of gastric cancer." (PMID 32703934, 2020).